ERRFI1 (ERBB receptor feedback inhibitor 1)
Diseases named in the same sentence as ERRFI1 in open-access papers (continued):
Sharing a sentence is not in itself a finding about the gene and the disease.
infection (2 papers, 2011 to 2019). The state of being infected such as from the introduction of a foreign agent such as serum, vaccine, antigenic substance or organism. "Additionally, a single gene Errfi1 was found to be upregulated in the transcriptome during all infections; potentially representing a unique marker of acute infection." (PMID 31546628, 2019). "In contrast, there was a greater activation of genes such as TNF-α, IL1A, IL8, JUN, ERRFI1 and KLF6 after infection with N. lactamica relative to N. meningitidis." (PMID 22028815, 2011). "We also noted the sustained upregulation of the transcript Errfi1 (MIG6 or RALT) across both 24 and 48 h post-infection for all three pathogens; although not in the top 10 upregulated transcripts where it was the only molecule common during all three infections." (PMID 31546628, 2019).
degenerative diseases (1 paper, 2021). "These include Spon2, Adam19, Arntl, Cdkn1a, Cry2, Per2, Per3, Wee1, Rcan1, Slc41a3, Errfi1, and Bhlhe41, which are related to numerous cardiovascular and degenerative diseases of other organs as well as varying aging processes." (PMID 33668521, 2021).
neurological disease (1 paper, 2025). "ERRFI1, CTXN3, IRX6, and IQCA1 have not yet been reported in association with neurological disease." (PMID 40944498, 2025).
ERRFI1 also shares sentences with these, for which no sentence is quoted: pancreatic cancer (4 papers); non-small cell lung carcinoma (3); Bladder cancer (2); triple-negative breast carcinoma (2); acute kidney injury (1); adenocarcinoma (1); anaplastic astrocytoma (1); anaplastic oligodendroglioma (1); asthma (1); astrocytoma (1); biliary tract cancer (1); cardiac hypertrophy (1); cervical cancer (1); Cirrhosis (1); colitis (1); colorectal cancer (1); cutaneous melanoma (1); endotoxemia (1); epilepsy (1); gastric cancer (1); hypothyroidism (1); inflammation (1); inflammatory bowel disease (1); intrahepatic cholangiocarcinoma (1); lung squamous cell carcinoma (1); oligodendroglioma (1); ovarian carcinoma (1); preeclampsia (1); prostate carcinoma (1); small cell lung carcinoma (1).
A further 2 diseases each share a sentence with ERRFI1 in 1 paper.